CD36 (CD36 molecule (CD36 blood group))
Diseases named in the same sentence as CD36 in open-access papers (continued):
Sharing a sentence is not in itself a finding about the gene and the disease.
non-alcoholic steatohepatitis (14 papers, 2013 to 2025). "Inhibition of CD36 palmitoylation reduces its hydrophobicity and accessibility to the plasma membrane and causes a decrease in the binding and uptake of long-chain FAs, such as palmitate, in hepatic cells, which protects mice from nonalcoholic steatohepatitis and fibrosis." (PMID 35500650, 2022). "NTS signaling is significantly upregulated in MASLD and in metabolic dysfunction-associated steatohepatitis (MASH) human liver samples when compared to normal livers, which correlates with the expression of CD36 and oxidative phosphorylation proteins." (PMID 40287434, 2025). "Regulating the RARα-PPARγ-CD36 cascade can reduce lipid accumulation and lipotoxicity in hepatocytes and reduce nonalcoholic steatohepatitis in mice." (PMID 37755746, 2023). "Miquilena-Colina and colleagues demonstrated that the expression of CD36 was up-regulated in the liver of patients with nonalcoholic steatohepatitis (NASH) and patients infected with HCV of genotype 1." (PMID 24016701, 2013). "Patients with non-alcoholic steatohepatitis exhibit elevated palmitoylation of CD36, which aggravates lipid accumulation and immune-cell infiltration in the liver 65, and tumor cells exhibiting metastatic potential express increased levels of CD36 and show elevated FA-uptake activity." (PMID 31410189, 2019).
pancreatic cancer (14 papers, 2015 to 2025). "In some pancreatic cancers, CD36 expression is negatively associated with tumor progression." (PMID 36497140, 2022). "Conversely, other studies have found that CD36 expression in pancreatic cancer cells and tissues is significantly lower than in corresponding normal tissues, with low CD36 expression predicting larger tumor size and poorer survival prognosis." (PMID 41267927, 2025). "Some studies suggest that in pancreatic tumors, CD36 promotes metastasis by regulating immune cell invasion, microvesicle extravasation, and the infiltration of specific tissue macrophages." (PMID 41267927, 2025). "A larger and more homogeneous cohort of samples would benefit the continuing study of CD36 expression in connection to pancreatic cancer with an emphasis on treatment resistance." (PMID 38370376, 2024). "It was demonstrated that CD36 has significantly lower expression in pancreatic cancer cells’ lines and tumor tissues." (PMID 32781778, 2020). "In a comparative study, exploring pancreatic cancer versus normal pancreatic tissue, CD36 was found to be significantly lower in cancer than in corresponding non-tumor normal tissues." (PMID 32781778, 2020). "Research has shown that CD36 expression is significantly reduced in pancreatic cancer cell lines and tumor tissues, which may enhance tumor cell motility by weakening ECM adhesion and collagen-binding capacity, thereby promoting metastasis and poor prognosis." (PMID 41383622, 2025). "This suggests that CD36 may serve as a predictor of clinical pathological features and prognosis in pancreatic cancer." (PMID 41267927, 2025). "However, CD36 was a controversial indicator in pancreatic cancer, low expression of CD36 predicted lower TNM staging and CA19-9 levels, but larger tumor size and poor survival prognosis." (PMID 32071556, 2020). "However, additional studies on the expression of the fatty acid transporter protein (FATP) CD36 in pancreatic cancer cells are needed." (PMID 28407685, 2017). "However, high expression of CD36 predicts a good prognosis for pancreatic cancer patients." (PMID 38184732, 2024). "Certain molecular key points outlined in pancreatic cancer, and mostly in PDAC, are connected to the TGFbeta pathway, including CD36." (PMID 32781778, 2020). "We observed increased CD36 expression in KPECs after REDD1 knockdown, in KRMEFs compared with KMEFs, and in vivo in human pancreas carcinomas with low REDD1 levels." (PMID 32273287, 2020). "A study elucidated that TGF-β1 could promote the expression of TSP-2 which in turn interacted with integrin αvβ3/CD36, and then activated MAPK signaling to drive the progression of pancreatic cancer." (PMID 35872838, 2022). "Several studies connect CD36 and TSP-1 to the TGFβ1 signaling, linking this to pancreatic cancer, providing information on another molecule involved in the process, PAI-1, which is upregulated in pancreatic cancer cells." (PMID 32781778, 2020). "Further studies are needed to gain insight into the concomitant impact of CD36 and CD97 on modulating fibroblasts phenotypes under different conditions, thus offering potential innovative therapeutic strategies to inactivate CAF and prevent aberrant tumor-stroma crosstalk in pancreatic cancer." (PMID 32781778, 2020).
breast tumor (13 papers, 2013 to 2025). "In summary, the reduction in CD36 expression observed in the vasculature surrounding premalignant lesions and fully invasive breast tumors coincided with a loss of PPARγ expression within the vasculature." (PMID 37816052, 2023). "In a study of breast tumor samples, high CD36 expression positively correlated with adipocyte infiltration." (PMID 39920872, 2025). "We found that CD36 expression was elicited following HER2-targeted therapy in human breast tumors and demonstrated that high CD36 levels in these tumors were significantly associated with worse clinical outcome in patients." (PMID 37371076, 2023). "In this study, we characterized the transfer of miR-200c from apoptotic MCF7 breast tumor cells to MΦ and identified CD36 as a critical receptor for its uptake." (PMID 35336722, 2022). "Protein expression of CD36 was detected at a low level in normal breast tissue and at a medium level in breast tumor tissue." (PMID 36114448, 2022). "When analyzed by immunohistochemistry, a minimal or null expression of CD36 was observed in normal tissue samples, whereas 35% of breast tumor samples have high CD36 expression, 46.7% have moderate expression, and only 18.3% low or null expression." (PMID 36568966, 2022). "IHC staining showed that a high proportion of breast tumours, with adipose tissue infiltration, have moderate to high CD36 expression." (PMID 34561446, 2021). "Analysis of E0771 breast tumor grafts showed that, although CD36 and PHB colocalized at the surface of intratumoral adipocytes, they were mainly intracellular in cancer cells." (PMID 34314388, 2021). "CD36 is overexpressed in breast tumors compared to normal tissue." (PMID 36568966, 2022). "The adipocyte marker CD36 is often used for distinguishing mesenchymal stem cells from bone marrow and adipose tissue; we observed high expression in all four of our normal and in one breast tumor ADSC primary cell lines." (PMID 26968831, 2016). "In human tissue microarray, consisting of normal and 180 human breast tumour samples, immunohistochemistry (IHC) revealed weak or no CD36 expression in seven of the nine normal patient tissues." (PMID 34561446, 2021).
lipid metabolism disorders (13 papers, 2013 to 2025). "Hydrogen inhibits fatty acid uptake and lipid accumulation through the downregulation of CD36 at the protein level in hepatic cultured cells, providing insights into the molecular mechanism underlying the hydrogen effects in vivo on lipid metabolism disorders." (PMID 23448206, 2013). "Therefore, it is possible the ECMR signaling impacts CD36, EC-derived exosomes, and associated lipid metabolic disorders." (PMID 37610001, 2023). "In this study, we found that miR-20a-5p played a protective role in lipid metabolic disorders of NAFLD by targeting CD36, which indicated the prospect of miR-20a-5p as a biomarker and treatment target for NAFLD." (PMID 33344451, 2020). "Therapeutic strategies aimed at inhibiting CD36 and activating ALH2 may offer dual benefits by ameliorating lipid metabolic disorders and reducing oxidative damage." (PMID 41287052, 2025).
liver disease (13 papers, 2014 to 2025). "Recent studies indicate that CD36 activation exacerbates metabolic dysfunction-associated steatotic liver disease in mouse models of type 2 diabetes." (PMID 40331957, 2025). "Although CD36 is implicated in NAFLD and HCC40,41, the molecular action of CD36 in liver disease has remained poorly defined." (PMID 31358770, 2019). "In addition, targeting the gut-liver axis or the liver-adipose tissue axis through CD36 could offer new strategies for managing metabolic disorders associated with liver disease." (PMID 39774047, 2025). "Understanding the role of CD36 in intercellular and interorgan crosstalk provides potential targets for therapeutic intervention in liver diseases." (PMID 39774047, 2025). "Glycosylated CD36 was shown to aid the intestine in absorbing LCFAs more quickly in patients with cirrhosis and portal hypertension." (PMID 39774047, 2025). "Further investigations are warranted to fully elucidate the therapeutic potential of targeting CD36 in liver diseases and to translate these findings into clinical practice." (PMID 39774047, 2025). "In the following review, we will focus on the latest advancements regarding CD36 in liver diseases and briefly discuss the potential of CD36 as a therapeutic target for liver diseases." (PMID 39774047, 2025). "Our review indicates a broad but underexplored research area involving the complex interplay between CD36 and the pathophysiology of liver diseases, and it summarizes current promising CD36-related therapies for liver disease." (PMID 39774047, 2025). "Currently, there is a clearer understanding of the biological functions and signaling pathways of CD36, with increasing evidence pointing to its significant role in the progression of liver diseases." (PMID 39774047, 2025). "Further studies are required to clarify the sources of sCD36, as well as to elucidate the mechanisms of CD36 involved in HBV-related liver diseases." (PMID 36406414, 2022). "Then, in this study we further investigated the clinical significance of CD36 in the progress of HBV-related liver diseases." (PMID 36406414, 2022). "Understanding the intricate mechanisms by which CD36 contributes to liver diseases may pave the way for the development of novel therapeutic strategies." (PMID 39774047, 2025). "Furthermore, the potential of CD36 as a therapeutic target for the prevention and treatment of liver diseases is highlighted." (PMID 39774047, 2025). "In addition, CD36 on intestinal epithelial cells can influence gut barrier function and the translocation of bacteria and their products, further contributing to liver disease." (PMID 39774047, 2025). "Notably, the high expression of CD36 in hepatocytes has been related to hepatic inflammation and fibrogenesis, which are closely correlated with hepatic diseases." (PMID 39596320, 2024). "The role of CD36 in liver disease has been recognized recently." (PMID 36406414, 2022). "Currently, increasing attention has been paid to the involvement of CD36 in liver diseases." (PMID 30016988, 2018). "Therefore, the present study aimed to investigate whether circulating soluble CD36 (sCD36) could serve as a diagnostic and prognostic biomarker for HBV-related liver diseases based on the clinic collected data." (PMID 36406414, 2022). "Previous research has shown that CD36 promotes the transport of oxLDL into double-negative regulatory T cells, inducing ferroptosis in these cells, which subsequently exacerbates liver immune homeostasis disruption and the progression of metabolic dysfunction-associated steatotic liver disease." (PMID 40331957, 2025). "Thus far, the significance of CD36 in human liver diseases remains unclear." (PMID 25310357, 2014). "Although a moderate correlation was observed between sCD36 and monocyte CD36 expression, CD36 expression on monocytes was not remarkably related to liver disease severity." (PMID 36406414, 2022).
parasitemia (13 papers, 2008 to 2022). "In this model, mice deficient in CD36 had higher parasitemia levels and higher mortality compared to CD36-sufficient mice." (PMID 21772838, 2012). "CD36 has an important role in the control of parasitemia during malaria by enhancing pro‐inflammatory responses and decreasing anti-inflammatory responses in the early stages of infection and increasing phagocytic activity of macrophages." (PMID 31662766, 2019). "Absence of CD36 expression on macrophages leads to diminished TNFα response during the acute blood stage which results in higher parasitemia and mortality rates." (PMID 31662766, 2019). "It has been suggested that the host utilises CD36 to control the parasitemia prior to host immune responses or to minimise pro-inflammatory responses." (PMID 25360558, 2014). "PbA-infected Fyn−/− animals achieved parasitemia and exhibited morbidity/mortality characteristics that were comparable to WT and CD36−/− mice." (PMID 23967147, 2013). "Taken together, the contradictory data about CD36 on inflammatory response to parasite and parasite produce indicate that further investigation is needed for the role of CD36 in parasitic infection." (PMID 22287954, 2012). "CD36-null mice also display defect in parasite clearance, earlier peak parasitemias, higher parasite densities, and higher mortality rates compared to wild-type mice." (PMID 22287954, 2012). "An agonist of Ppar-γ enhanced the clearance of iRBCs of P. falciparum in vitro and improved the survival rate of mice infected with P. berghei and reduced parasitemia in the P. chabaudi chabaudi model in a CD36 dependent manner." (PMID 20531941, 2010). "It would be relevant to investigate if Cd36−/− mice infected with Leishmania major, Toxoplasma gondii and Trypanosoma cruzi, display higher levels of parasitemia and/or mortality, such as for P. chabaudi chabaudi AS." (PMID 19847289, 2009). "Furthermore, rosiglitazone reduces the parasitemia in a CD36-dependent manner in the Plasmodium chabaudi chabaudi hyperparasitemia model and improves the survival rate even when treatment is initiated as late as day 5 after infection." (PMID 22287954, 2012). "Cd36−/− mice also showed a higher level of parasitemia and mortality than wild-type mice." (PMID 19847289, 2009). "To study the involvement of CD36 in the pathogenesis of Pb infection, we compared parasitemia in normal C57BL6 and the CD36−/− mice infected with ANKA strain." (PMID 34858976, 2021). "Thus, at high IRBC doses, which are unlikely to be biologically relevant as parasitemia is low at early stages of infection, it is not possible to distinguish between the CD36-dependent and CD36-independent uptake mechanisms." (PMID 24204889, 2013). "However, Cd36−/− mice developed significantly less ALI during PbA infection compared to their wild type counterparts, as measured by BALF IgM concentration (2-tailed t-test, p<0.0001), despite having an equivalent parasitemia." (PMID 18483551, 2008).
tuberculosis (13 papers, 2010 to 2025). A chronic, recurrent infection caused by the bacterium Mycobacterium tuberculosis. "Despite facing numerous challenges, researches on the correlation between CD36 and M. tuberculosis infection have laid an experimental and theoretical foundation for CD36 to become a diagnostic marker of tuberculosis." (PMID 38881887, 2024). "If our observations are subsequently confirmed in human infection, it is conceivable that M. tb, being highly prevalent and virulent, could in part account for the persistence of CD36 deficiency in populations from tuberculosis-endemic regions." (PMID 20950462, 2010). "Based on the hypothesis that CD36 deficiency may alter host susceptibility to tuberculosis, we examined the role of CD36 in mycobacterial infection in vitro and in an experimental model in vivo." (PMID 20950462, 2010). "Although the underlying molecular mechanisms remain unclear and require further investigation, our study nevertheless suggests a unique role of CD36 in host susceptibility to tuberculosis." (PMID 20950462, 2010). "In summary, our findings indicate a novel role for CD36 in host response to mycobacterial infection and suggest that future population-based studies to examine the relationship between CD36 deficiency and susceptibility to tuberculosis would be of interest." (PMID 20950462, 2010). "Gene polymorphisms of MARCO and CD36 may contribute to tuberculosis risk." (PMID 28693442, 2017). "A large amount of clinical trial data indicated that CD36 is downregulated in the peripheral blood of tuberculosis patients, which is beyond doubt." (PMID 38881887, 2024). "CD36 plays an indispensable role in macrophage resistance against Mycobacterium infection, and the abnormality of CD36 is closely related to the inflammatory response of cells and the phagocytosis of tuberculosis." (PMID 38881887, 2024). "Recent research on CD36’s function in infectious disorders has shown that it plays a pathological role in infections with viruses, tuberculosis, pneumonia and Staphylococcus aureus." (PMID 38881887, 2024). "A similar mechanism involving nuclear receptor mediated upregulation of CD36 expression has been proposed in tuberculosis, but there are also the homeostatic mechanisms which function to balance lipid influx and efflux by macrophages in in vivo systems." (PMID 32407412, 2020). "We used BCG in vivo and BCG, M. marinum, and M. tb in vitro to model aspects of tuberculosis in order to dissect the role of CD36 in disease pathogenesis." (PMID 20950462, 2010). "Additionally, a growing body of research has revealed that patients with active tuberculosis (ATB) exhibit reversible changes in CD36 on their peripheral macrophages/monocytes." (PMID 38881887, 2024). "The functions of CD36 in M. tuberculosis infection has gradually become clear, and numerous studies are conducting animal and drug experiments targeting CD36, hoping to therapy tuberculosis." (PMID 38881887, 2024). "The scavenger receptor CD36 may have several important functions in the pathogenesis of tuberculosis." (PMID 22493658, 2012). "Furthermore, reversible alterations in the expression of CD36 on peripheral monocytes/macrophages have been observed in patients with active tuberculosis." (PMID 20950462, 2010). "Because CD36 is an important receptor for the uptake of OxLDL in other diseases, the increased expression of CD36 and OxLDL in M. tuberculosis infected guinea pigs may reflect their importance in the pathogenesis of tuberculosis as well." (PMID 22493658, 2012). "In tuberculosis (TB), M. tuberculosis infection activates TGF-β signaling through the upregulation of THBS1/2 and CD36." (PMID 40563563, 2025). "During tuberculosis, BLR49653 treatment had the same effect on CD36 expression and FM formation; in silicosis, PPARγ antagonist GW9662 treatment downregulated CD36 expression and inhibited FM formation." (PMID 35432274, 2022).
tuberculosis (continued). "In addition, among these differential proteins, LBP, CD36, and MHC-I attracted our interest and these three molecules are closely related to the infection of tuberculosis, especially CD36." (PMID 35069505, 2021). "In contrast to earlier reports supporting a role for PPARγ in regulating CD36 expression during tuberculosis, our results could not demonstrate a significant involvement of PPARγ in HKMT-mediated modulation of CD36 expression." (PMID 38989454, 2024).